RNU6-74P (RNA, U6 small nuclear 74, pseudogene)
Synonyms: RNU6-74
Gene: Small nuclear RNA gene on chromosome 13 (41,905,118 to 41,905,224, forward strand). Ensembl gene ENSG00000206962.
Homologues: Orthologues: macaque U6 (95% identical), guinea pig U6 (73% identical). Paralogues in human: RNU6-1145P (93% identical), RNU6-38P (92% identical), RNU6-1316P (91% identical), RNU6-25P (91% identical), RNU6-29P (91% identical), RNU6-393P (91% identical), RNU6-41P (91% identical), RNU6-1 (90% identical), RNU6-116P (90% identical), RNU6-15P (90% identical), RNU6-2 (90% identical), RNU6-35P (90% identical), and 1285 more.